NUAK1 (NUAK family kinase 1)
Description:
Serine/threonine-protein kinase involved in various processes such as cell adhesion, regulation of cell ploidy and senescence, cell proliferation and tumor progression. Acts as a regulator of cellular senescence and cellular ploidy by mediating phosphorylation of 'Ser-464' of LATS1, thereby controlling its stability. Controls cell adhesion by regulating activity of the myosin protein phosphatase 1 (PP1) complex. Acts by mediating phosphorylation of PPP1R12A subunit of myosin PP1: phosphorylated PPP1R12A then interacts with 14-3-3, leading to reduced dephosphorylation of myosin MLC2 by myosin PP1. May also act as a tumor malignancy-associated factor by promoting tumor invasion and metastasis under regulation and phosphorylation by AKT1. Suppresses Fas-induced apoptosis by mediating phosphorylation of CASP6, thereby suppressing the activation of the caspase and the subsequent cleavage of CFLAR. Regulates UV radiation-induced DNA damage response mediated by CDKN1A. In association with STK11, phosphorylates CDKN1A in response to UV radiation and contributes to its degradation which is necessary for optimal DNA repair.
Synonyms: ARK5; KIAA0537
Tractability: Small molecule: a high-quality ligand is known; it belongs to a druggable protein family. PROTAC: it is named in the literature on targeted protein degradation; UniProt records ubiquitination sites on it; a small molecule that binds it is known.
Target class: Enzyme; Protein Kinase; Kinase; CAMK protein kinase group; CAMK protein kinase NuaK subfamily; CAMK protein kinase CAMK1 family
Chemical probes: HTH-02-006 (high quality), WZ4003 (high quality)
Safety:
Unwanted effects reported when the protein is acted on. In parentheses: how it was acted on, where the effect was seen, and who reports it.
cardiac arrhythmia (cardiovascular system; source: Lamore et al. (2017))
Gene: Protein-coding gene on chromosome 12 (106,063,345 to 106,138,954, reverse strand). Ensembl gene ENSG00000074590.
Subcellular location: Nucleus; Cytoplasm
Subcellular location (Human Protein Atlas): Nucleoli fibrillar center; Microtubules; Mitotic spindle; Nucleoplasm; Primary cilium
Gene Ontology:
Molecular function: protein binding; protein serine/threonine kinase activity; ATP binding; protein kinase activity; protein serine kinase activity
Biological process: protein phosphorylation; regulation of cell adhesion; regulation of cellular senescence; regulation of cell population proliferation
Cellular component: cytoplasm; fibrillar center; nucleoplasm; nucleus
Genetic constraint (gnomAD): Loss-of-function variants: 26 observed, 56.63 expected, observed/expected ratio (o/e) 0.46, 90% interval 0.34 to 0.64. The upper end of that interval is the gene's LOEUF score, 0.64, which puts it in group 2 of 6, group 1 being the genes least tolerant of losing a copy. Missense variants: 727 observed, 909.66 expected, observed/expected ratio (o/e) 0.8, 90% interval 0.75 to 0.85. Synonymous variants: 337 observed, 351.03 expected, observed/expected ratio (o/e) 0.96, 90% interval 0.88 to 1.05.
Homologues: Orthologues: chimpanzee NUAK1 (99% identical), macaque NUAK1 (99% identical), pig NUAK1 (94% identical), dog NUAK1 (92% identical), mouse Nuak1 (91% identical), rat Nuak1 (91% identical), guinea pig NUAK1 (76% identical), tropical clawed frog nuak1 (74% identical), rabbit NUAK1 (67% identical), zebrafish nuak1b (60% identical), zebrafish nuak1a (59% identical), Drosophila melanogaster Nuak (38% identical), and 5 more. Paralogues in human: NUAK2 (55% identical), SIK1 (27% identical), SIK2 (27% identical), SIK3 (26% identical), BRSK2 (24% identical), BRSK1 (23% identical), PRKAA1 (23% identical), PRKAA2 (23% identical), MELK (23% identical), SNRK (22% identical), HUNK (21% identical), TSSK1B (20% identical), and 5 more.
Diseases named in the same sentence as NUAK1 in open-access papers:
NUAK1 is named in the same sentence as 76 diseases in open-access papers, as found by Europe PMC text mining. Sharing a sentence is not in itself a finding about the gene and the disease. The quoted sentences say what the papers report.
breast carcinoma (22 papers, 2015 to 2025). "In HER2-enriched breast cancer, higher NUAK1 expression was associated with worse patient survival in both pre- and post-chemotherapy groups." (PMID 34084284, 2021). "To uncover the association between miR-622 and NUAK1 expression in breast cancer patients, we consulted several public data sets, available from the Gene Expression Omnibus (GEO) database." (PMID 32418991, 2020). "NUAK1 kinase is a functional target of miR-622, it is associated with poor clinical outcomes of breast cancer patients and is inversely correlated with miR-622 level." (PMID 32418991, 2020). "Deletion of NUAK1 or STK11 (encoding LKB1) was each identified as synthetic lethal with PTEN loss in breast cancer, and loss of either NUAK1 or STK11 drives a requirement for increased NFκB activity in ovarian cancer, again linked to suppression of oxidative stress." (PMID 36975767, 2023). "The risk score of breast cancer patients was calculated using the following formula: Risk score = −0.482 * expression of CPEB1 + 0.468 * expression of NOTCH3 + 0.213 * expression of NUAK1 + 0.321 * expression of PDPK1." (PMID 36072578, 2022). "RNAi-based screening for synthetic lethal interactions with loss of PTEN in breast cancer identified NUAK1, along with STK11 and PIK3CB, suggesting functional interaction between the LKB1-NUAK1 and PI3K-AKT pathways." (PMID 38939918, 2024). "ON123300, a multi-kinase inhibitor with high specificity for CDK4/CDK6 and NUAK1, showed a strong anti-tumorigenic effect on breast cancer, glioblastoma, lymphoma, and multiple myeloma and reduced Akt phosphorylation." (PMID 38135881, 2023). "Overexpression of NUAK1 in MDA-MB-231 breast cancer cells increases the migration and invasion potential of these cells in an Akt-dependent manner, suggesting a role for NUAK1 in EMT and metastasis." (PMID 34685740, 2021). "For example, NUAK1 and NUAK2 downregulation has been linked to reduced motility and invasiveness of renal and breast cancer cell lines, whereas overexpression of NUAK2 in HepG2 human hepatocytes increases survival following glucose starvation." (PMID 34685740, 2021). "Akt-dependent NUAK1 activation increases breast cancer metastatic potential in MDA-MB-231 highly metastatic (MDA-MB-213HM) breast cancer cells." (PMID 34685740, 2021). "miR-622/NUAK1 axis is deregulated in breast cancer patients and affects the motility phenotype of breast cancer cells." (PMID 32418991, 2020). "Here, we showed that miR-622 is downregulated in the plasma and in tissue samples of breast cancer patients where it acts as a tumour suppressor by reducing cell migration and invasion through targeting NUAK1 kinase." (PMID 32418991, 2020). "Multiple cancers overexpress NUAK1, such as hepatocarcinoma, colon cancer, glioma, and breast cancer within others." (PMID 32754444, 2020). "The aim of this study was to analyse the miR-622 level in the plasma and in tissues of breast cancer patients and to explore the role of miR-622 and its target, the NUAK1 kinase, in this context." (PMID 32418991, 2020). "Taken together, our novel findings demonstrated that NUAK1 is a direct target of miR-622 in breast cancer cells." (PMID 32418991, 2020). "Altogether, our data suggest that the cytosolic NUAK1 enhances breast cancer cell bioenergetics by increasing the mitochondrial respiratory capacity." (PMID 32754444, 2020). "Given the importance of ER, PR and HER2 status as prognostic factors for breast cancer outcomes, we also studied the correlation between NUAK1 and RFS in each cancer subtype." (PMID 32418991, 2020). "In conclusions, our findings provide evidence that miR-622 and NUAK1 are potential novel biomarkers and targets for breast cancer." (PMID 32418991, 2020). "Decreased expression of miR-204 is associated with poor prognosis in patients with breast cancer In NSCLC, miR-204 has been found to inhibit metastasis of NSCLC through the suppression of NUAK1." (PMID 30981205, 2019).
breast carcinoma (continued). "Two genes associated with pig melanoma (IRS1, NUAK1) were described as potential key players in human melanoma tumors and EPB41L4A-AS2 showed tumor suppressor features in breast cancer." (PMID 29963229, 2018). "Our findings are in line with previous studies reporting increases in cell death by NUAK1 silencing in colorectal cancer cells, reduced survival of breast cancer cells by silencing of NUAK2, and reduced proliferation of cervical cancer cells by silencing of NUAK2." (PMID 37188272, 2023). "However, the specific mechanisms of NUAK1 in breast cancer progression are unclear and need further exploration." (PMID 36072578, 2022). "Through targeting the NUAK1 kinase, miR-622 inhibited the motility phenotype of breast cancer." (PMID 36072578, 2022). "Indeed, NUAK1-overexpressing MDA-MB-231 cells were able to induce pulmonary metastasis in nude mice to a higher extent than breast cancer control cells." (PMID 34685740, 2021). "Furthermore, we showed that miR-622 tumour suppressor activity in breast cancer cells is mediated by direct targeting the NUAK1 kinase." (PMID 32418991, 2020). "Thus, our data provide evidence to support the role of NUAK1 as novel prognostic biomarker in predicting survival rate of specific subtypes of breast cancer patients." (PMID 32418991, 2020). "Based on the data accumulated, we explored whether miR-622 affected NUAK1 expression in the MDA-MB-231 breast cancer cell line." (PMID 32418991, 2020). "Since NUAK1 is a key component of the antioxidant stress response pathway, we investigated if the induction of oxidative stress modulates miR-622/NUAK1 axis in breast cancer." (PMID 32418991, 2020). "Having demonstrated that miR-622 is able to inhibit the motility phenotype of breast cancer cells, we next sought to determine whether the restoration of NUAK1 expression is able to revert the functions of miR-622." (PMID 32418991, 2020). "Thus, our data provide evidence to support the role of NUAK1 in predicting survival rate in breast cancer patients." (PMID 32418991, 2020). "Additionally, NUAK1 is a positive regulator of cell cycle progression in breast cancer cells." (PMID 34504167, 2021). "Additionally, a recent paper reported that the inhibition of NUAK1 enhances cisplatin cytotoxicity in NSCLC cells suggesting that also in breast cancer NUAK1 could represent a novel target against drug resistance." (PMID 32418991, 2020). "Importantly, miR-622 and NUAK1 hold promises as biomarkers and as targets for breast cancers." (PMID 32418991, 2020). "Initial reports regarding NUAK1 and NUAK2 function indicate a potential role in apoptosis resistance as assessed in MCF7 human breast cancer cells following starvation." (PMID 34685740, 2021). "CD95-induced apoptosis is severely impeded when NUAK1 and NUAK2 proteins were silenced in MCF7 breast cancer, human cervix carcinoma (HeLa), and colorectal cancer cell lines." (PMID 34685740, 2021). "To further confirm the role of the cytosolic NUAK1 in breast cancer cells, we used MDA-MB-231 cells, where NUAK1 only detected in the cytosolic fraction." (PMID 32754444, 2020). "In addition, the expression levels of CPEB1, NOTCH3, NUAK1, and PDPK1 were significantly discrepant among the molecular subtypes of breast cancer." (PMID 36072578, 2022). "Additionally, we have examined a possible connection between YAP expression and miR-622 in breast cancer cells and found that YAP overexpression induced a reduction of miR-622 and an increase of NUAK1 levels." (PMID 32418991, 2020). "Kaplan–Meier curves showed that NUAK1 represents a predictor factor of greater RFS, not in whole population of breast cancer patients, but only into specific subtypes: ER- negative, HER2-positive and luminal B subtypes." (PMID 32418991, 2020).
breast carcinoma (continued). "Our identification of NUAK2 but not NUAK1 in the TNBC lines, an observation we confirmed in separate studies, suggests that NUAK2, rather than NUAK1, may play a more prominent role in promoting YAP/TAZ activity in breast cancer." (PMID 40869130, 2025).
colorectal cancer (18 papers, 2015 to 2025). A primary or metastatic malignant neoplasm that affects the colon or rectum. "More recently, NUAK1 overexpression was reported to be associated with poor prognosis in a murine model of colorectal cancer." (PMID 34685740, 2021). "NUAK1 is associated with cancerous invasion in breast and lung cancers, colorectal carcinoma, and multiple myeloma." (PMID 26882562, 2016). "NUAK1 has been reported to inactivate glycogen synthase kinase-3 beta (GSK3β) by suppressing the de-phosphorylation pathway of GSK3β Ser9 in colorectal cancer cells." (PMID 39901136, 2025). "In the realm of tumor therapy, the triple—combination therapy (NUAK1 inhibitor + statin + PD—1 antibody) developed by a research team for colorectal cancer serves as a representative instance." (PMID 40877572, 2025). "In colorectal cancer, depletion or inhibition of NUAK1 renders human colorectal cancer cells and murine colorectal tumors vulnerable to oxidative stress-induced cell death." (PMID 37919754, 2023). "NUAK1 shows higher expression in advanced stage colorectal cancers and in biopsies from liver metastatic sites, compared to primary tumors." (PMID 36295658, 2022). "For example, the overexpression of NUAK1 has been linked to a poor prognosis in ovarian and colorectal cancers, and the oncogenic role of TNIK is deemed important in colorectal cancer." (PMID 35267421, 2022). "Studies performed in the mouse Kirsten rat sarcoma viral oncogene (KRAS) Cre-inducible model of colorectal cancer showed that NUAK1 was detected in spheroids released from tumor cells." (PMID 34685740, 2021). "After oxidative stress, the expression of NUAK1 in colorectal cancer is increased, leading to a decrease in the invasive height and overall survival rate of colorectal cancer." (PMID 33505587, 2021). "Aberrant expression of NUAK1 has been observed in patients diagnosed with multiple cancer types including prostate cancer, nasopharyngeal carcinoma, pancreatic cancer and colorectal cancer." (PMID 37919754, 2023). "High levels of expression of NUAK1 (ARK5) have been reported to correlate with poor prognosis in patients with hepatocellular carcinoma, glioma, colorectal cancer, multiple myeloma and pancreatic cancer." (PMID 26196184, 2015). "Depletion of NUAK1 in bone cancer cell lines (U2OS) and different colorectal cancer cell lines triggers sensitization to oxidative stress and consequently cell death." (PMID 34685740, 2021).
ovarian carcinoma (12 papers, 2016 to 2024). A malignant neoplasm originating from the surface ovarian epithelium. "High expression of NUAK1 is associated with poor outcome in ovarian cancer where it promotes metastasis, in part via upregulation of fibronectin." (PMID 36975767, 2023). "Previously, high NUAK1 expression was associated with poor prognosis in glioma, ovarian cancer (OV), and non-small cell lung cancer (NSCLC)." (PMID 38135881, 2023). "In summary, these data indicate that NUAK1 upregulation is associated with bad prognosis in ovarian cancer patients and in female glioma patients, suggesting an interesting correlation between ovarian and brain cancers." (PMID 34685740, 2021). "Using publicly available transcript expression data from 1,262 ovarian cancer patients, we show that elevated NUAK1 is associated with decreased OS and PFS." (PMID 27833898, 2016). "On the other hand, NUAK1 has been demonstrated to play an important role in the development of ovarian cancer." (PMID 34685740, 2021). "Aside from the regulation of miR-1181 in ovarian cancer cells, NUAK1 overexpression has been shown to correlate with poor prognosis in ovarian cancer." (PMID 34685740, 2021). "Accordingly, an independent in vitro study demonstrated that NUAK1 downregulation reduces invasion of ovarian cancer cells." (PMID 34685740, 2021). "Altogether, our findings suggest that LKB1 regulates NUAK1 expression in ovarian cancer spheroids and tumour samples." (PMID 32429240, 2020). "We have also observed that the NUAK1 gene exhibits worst prognosis in ovarian cancer (log rank p = 6.2e-9, n = 2,450)." (PMID 31217513, 2019). "We were able to validate the relationship between NUAK1 expression and OS in an independent cohort of 174 ovarian cancer patients with Agilent data." (PMID 27833898, 2016). "Indeed, knockdown of NUAK1 remarkably suppressed the tumor cell invasion and metastasis in gastric cancer, nasopharyngeal carcinoma and ovarian cancer." (PMID 37919754, 2023). "Although several studies previously showed that high expression of NUAK1 is positively associated with EMT, migration and invasion in gastric cancer, ovarian cancer, pancreatic cancer and lung cancer, the underlying molecular mechanisms remain poorly understood." (PMID 37919754, 2023). "Moreover, in epithelial ovarian cancer, NUAK1 promotes cell adhesion, spheroid compaction and metastasis through regulation of fibronectin expression and matrix production." (PMID 37919754, 2023). "Indeed, the Protein Atlas database indicates that NUAK1 upregulated expression is correlated with bad prognosis in ovarian cancer." (PMID 34685740, 2021). "Indeed, NUAK1 downregulation in SKOV3 ovarian cancer cells reduced chemotaxis in an epidermal growth factor 1 (EGF-1)-induced experiment." (PMID 34685740, 2021). "Finally, experimental procedures performed in two independent cohorts of ovarian cancer patient samples indicate that NUAK1 is one of the most upregulated genes in patient samples with poor prognosis of the disease." (PMID 34685740, 2021). "NUAK1 transcript expression was assessed in a cohort of 1,262 patients assembled from seven publicly available, ovarian cancer Affymetrix microarray data sets downloaded from the curatedOvarianData database and an independent cohort of 174 HGSOC patients with Agilent gene expression data." (PMID 27833898, 2016). "Consequently, the NUAK1 correlation with poor prognosis in ovarian cancer might be partially due to increased migration and invasion." (PMID 34685740, 2021). "Furthermore, the importance of NUAK1 in ovarian cancer has been demonstrated in tumor development." (PMID 34685740, 2021). "NUAK1 upregulation has been reported in ovarian cancer and silencing of NUAK1 results in reduced cell migration in HEY ovarian cancer cells." (PMID 34685740, 2021).